ZCCHC9 (zinc finger CCHC-type containing 9)
Description:
May down-regulate transcription mediated by NF-kappa-B and the serum response element.
Synonyms: DKFZp761J139; PPP1R41
Tractability: No criterion of Open Targets' tractability assessment is met for any kind of drug.
Gene: Protein-coding gene on chromosome 5 (81,301,583 to 81,313,766, forward strand). Ensembl gene ENSG00000131732.
Subcellular location: Nucleus, nucleolus; Nucleus
Subcellular location (Human Protein Atlas): Nucleoplasm; Nucleoli
Gene Ontology:
Molecular function: RNA binding; nucleic acid binding; zinc ion binding
Cellular component: nucleolus; nucleoplasm; nucleus
Genetic constraint (gnomAD): Loss-of-function variants: 14 observed, 27.08 expected, observed/expected ratio (o/e) 0.52, 90% interval 0.34 to 0.81. The upper end of that interval is the gene's LOEUF score, 0.81, which puts it in group 3 of 6, group 1 being the genes least tolerant of losing a copy. Missense variants: 254 observed, 313.72 expected, observed/expected ratio (o/e) 0.81, 90% interval 0.73 to 0.9. Synonymous variants: 87 observed, 100.23 expected, observed/expected ratio (o/e) 0.87, 90% interval 0.73 to 1.04.
Homologues: Orthologues: chimpanzee ZCCHC9 (99% identical), macaque ZCCHC9 (98% identical), dog ZCCHC9 (93% identical), pig ZCCHC9 (89% identical), guinea pig ZCCHC9 (86% identical), rat Zcchc9 (84% identical), mouse Zcchc9 (83% identical), rabbit ZCCHC9 (72% identical), tropical clawed frog zcchc9 (55% identical), zebrafish zcchc9 (50% identical), Caenorhabditis elegans F07E5.5 (34% identical). Paralogues in human: ZCCHC7 (18% identical), ZCCHC13 (14% identical), CNBP (14% identical).
Diseases named in the same sentence as ZCCHC9 in open-access papers:
ZCCHC9 is named in the same sentence as 1 disease in open-access papers, as found by Europe PMC text mining. Sharing a sentence is not in itself a finding about the gene and the disease. The quoted sentences say what the papers report.
cancer (1 paper, 2024). A tumor composed of atypical neoplastic, often pleomorphic cells that invade other tissues. "Again, selective upregulation of transcriptional and epigenetic regulators in responders is evident; examples include PRDM5, ZNF230, ZCCHC9, ZKSCAN4, and the epigenetic regulator ALKBH3, which demethylates DNA and RNA in cancer cells." (PMID 39450169, 2024).